SV2A (synaptic vesicle glycoprotein 2A)
Diseases named in the same sentence as SV2A in open-access papers (continued):
Sharing a sentence is not in itself a finding about the gene and the disease.
Parkinson’s (2 papers, 2024 to 2025). "The spatial and temporal pattern of SV2A could help to explain PD pathology, distinguish between atypical Parkinsonism’s, and could act as a therapeutic biomarker." (PMID 40672937, 2025).
progressive supranuclear palsy (2 papers, 2022 to 2024). A rare late-onset neurodegenerative disease characterized by supranuclear gaze palsy, postural instability, progressive rigidity, and mild dementia. "A decrease of synaptic SV2A density was assessed in a study of progressive supranuclear palsy (Richardson’s syndrome) and in amyloid-negative corticobasal syndrome." (PMID 35573314, 2022).
status epilepticus (2 papers, 2016 to 2021). Status epilepticus is defined as a continuous seizure lasting more than 30 min, or two or more seizures without full recovery of consciousness between any of them. "Moreover, SV2A–null mice have been reported dying at approximately P15 in status epilepticus." (PMID 27861538, 2016).
tetanus (2 papers, 2019 to 2022). A serious infectious disorder that follows wound contamination by the Gram-positive bacterium Clostridium tetani. "It has been shown that SV2 proteins (particularly SV2A and SV2B isoforms) are also responsible for the neuronal entry of tetanus toxins that cause rigid paralysis." (PMID 35573314, 2022). "Botulinum neurotoxin A (BoNT/A) binds to a ganglioside and a synaptic vesicle protein SV2A/B/C, BoNT/B binds to a ganglioside and a synaptic vesicle protein Synaptotagmins I/II while Tetanus neurotoxin binds to dual-gangliosides." (PMID 30862940, 2019).
amyotrophic lateral sclerosis (1 paper, 2022). Amyotrophic lateral sclerosis (ALS) is a neurodegenerative disease characterized by progressive muscular paralysis reflecting degeneration of motor neurons in the primary motor cortex, corticospinal tracts, brainstem and spinal cord. "Altogether, these observations support the exploration of SV2A PET imaging as a synaptic integrity marker in spinal cord–related disorders, such as amyotrophic lateral sclerosis, as well as spinal cord injury." (PMID 34531262, 2022).
Atrophy (1 paper, 2025). Any weakening or degeneration, especially through lack of use. "This further supports the additive information of [18F]SynVesT-1 PET relative to MRI atrophy markers and suggests that increased density of SV2A may offset the effects of lower cortical volume on cognition." (PMID 40049743, 2025).
behavioural disorders (1 paper, 2021). "The scarce tolerability of LEV would not lead to a higher risk of BRV behavioural disorders, probably because the latter does not interact with AMPA receptors and has a more selective effect on SV2A." (PMID 34131547, 2021).
breast carcinoma (1 paper, 2026). "Research shows that botulinum neurotoxin type A (BoNT/A), which binds to SV2A, the BoNT/A receptor, can inhibit the growth of prostate and breast cancer cells, suggesting its potential as an alternative treatment for breast cancer." (PMID 42188614, 2026).
cortical dysplasia (1 paper, 2022). "A limited number of studies have measured SV2A levels in the human neocortex with intractable epilepsy and cortical dysplasia." (PMID 35578248, 2022).
Dyskinesia (1 paper, 2024). A movement disorder which consists of effects including diminished voluntary movements and the presence of involuntary movements. "Levetiracetam's inhibition of synaptic vesicle glycoprotein 2A and alteration of GABA metabolism and turnover in the striatum may contribute to dyskinesia by influencing striatal dopamine release." (PMID 39036275, 2024).
Dysphagia (1 paper, 2025). "On such a substrate, levetiracetam’s broad presynaptic reduction of transmitter release at both excitatory and inhibitory terminals (via SV2A) may further depress the already unstable swallow CPG output, aggravating dysphagia until the drug is withdrawn." (PMID 41041452, 2025).
epithelial ovarian cancer (1 paper, 2023). "We found that the loss of CTGF in epithelial ovarian cancer cells is associated with modifications on the expression of several genes associated with the ECM, including LAMC2 SPP1, SV2A, RELN, COL6A3, and COL4A6." (PMID 37835529, 2023).
essential tremor (1 paper, 2025). A relatively common disorder characterized by a fairly specific pattern of tremors which are most prominent in the upper extremities and neck, inducing titubations of the head. "However, SV2A quantification via [18F]SDM-16 radioligand in post-mortem essential tremor patients showed ∼50% reduction in synaptic density in the cerebellar cortex compared with controls." (PMID 40672937, 2025).
focal cortical dysplasia type II (1 paper, 2022). "The loss of synaptic vesicle glycoprotein 2A (SV2A) is well established as the major correlate of epileptogenesis in focal cortical dysplasia type II (FCD II), but this has not been directly tested in vivo." (PMID 34978594, 2022).
glioblastoma (1 paper, 2020). The most malignant astrocytic tumor (WHO grade IV). "High transcript levels in glioblastoma were measured for SNAP-25, the synaptic vesicle glycoprotein 2A (SV2A), and for synaptophysin." (PMID 32292341, 2020).
ischemia (1 paper, 2021). A hypoperfusion of the BLOOD through an organ or tissue caused by a PATHOLOGIC CONSTRICTION or obstruction of its BLOOD VESSELS, or an absence of BLOOD CIRCULATION. "A previous study has shown that 3-day treatment with levetiracetam maintained SV2A protein expression via interaction with astrocytes, which influenced the OPC lineage through activation of CREB to protect white matter from ischemia." (PMID 34054520, 2021).
ocular hypertension (1 paper, 2022). Abnormally high intraocular pressure. "Low expression or dysfunction of SV2A has been shown to initiate neurodegenerative processes, including neuronal apoptosis, axon damage, and synapse loss, in AD and ocular hypertension." (PMID 36362420, 2022).
painful bladder syndrome (1 paper, 2015). "A recent investigation demonstrated that patients with idiopathic detrusor overactivity and those with painful bladder syndrome both have more SV2A nerve fibers than the controls." (PMID 26241848, 2015).
photosensitive epilepsy (1 paper, 2025). An epilepsy characterized by seizures triggered by visual stimuli that form patterns in space or time, such as flashing lights. "Thus, SV2A is a very attractive candidate gene in the context of photosensitive epilepsy." (PMID 40411480, 2025).
prostate adenocarcinoma (1 paper, 2021). "According to in silico data, we found a dim positivity for SV2A in prostate adenocarcinoma cells and some positive infiltrating stroma cells, whereas a strong and homogeneous expression of SV2A characterized NEPC." (PMID 33737929, 2021). "We found that the protein target of levetiracetam, SV2A, is highly expressed by both NEPC cells and MCs infiltrating prostate adenocarcinoma, while it is low or negligible in adenocarcinoma cells." (PMID 33737929, 2021).
proteinopathy (1 paper, 2020). "Our review shows that multiple new tracers have been developed for proteinopathy targets, particularly tau, as well as the purinoceptor P2X7, phosphodiesterase enzyme PDE10A, and synaptic vesicle glycoprotein 2A (SV2A), amongst others." (PMID 31541283, 2020).
sarcopenia (1 paper, 2020). Progressive decline in muscle mass due to aging which results in decreased functional capacity of muscles. "LASSO regression model was used to select 4 key differentially expressed (SEPP1, GFOD1, GOT1, and SV2A) mRNAs (DEMs) predictors of sarcopenia risk and the lasso parameter (lambda.min) was 0.01038519." (PMID 33221762, 2020). "A new prediction model with high accuracy can be developed based on four identified molecular markers (SEPP1, SV2A, GOT1, and GFOD1) and used by clinicians to predict the risk of sarcopenia." (PMID 33221762, 2020). "SEPP1 mRNAs were upregulated and GFOD1, GOT1, and SV2A mRNAs were downregulated in the sarcopenia group." (PMID 33221762, 2020). "Combined with the nomogram prediction model results, SEPP1, GFOD1, GOT1, and SV2A may be key modulators of sarcopenia." (PMID 33221762, 2020). "Interestingly, the results of LASSO regression in this study reveals that the four characteristic factors (SEPP1, GOT1, GOFD1, and SV2A) have an important role in the prediction of sarcopenia." (PMID 33221762, 2020). "A new model for predicting sarcopenia based on four molecular markers SEPP1, SV2A, GOT1, and GFOD1 was developed." (PMID 33221762, 2020). "Besides, this study is the first to predict the occurrence of sarcopenia based on four molecular markers (SEPP1, SV2A, GOT1, and GFOD1)." (PMID 33221762, 2020). "SEPP1 and DLEU2 expression levels were higher in patients with sarcopenia than in patients without sarcopenia, while the expression levels of GFOD1, GOT1, SV2A, and miR-181a were significantly lower in patients with sarcopenia than in patients without sarcopenia." (PMID 33221762, 2020).
Stroke (1 paper, 2022). Sudden impairment of blood flow to a part of the brain due to occlusion or rupture of an artery to the brain. "Further, the SV2A radiotracer UCB-J has allowed further study into post-stroke neuroplasticity." (PMID 41541584, 2022).
systemic lupus erythematosus (1 paper, 2022). An autoimmune multi-organ disease typically associated with vasculopathy and autoantibody production. "It was reported that in an inflammatory mouse model of neuropsychiatry systemic lupus erythematosus microglial cells are activated and showed an elevated uptake of synaptic material via staining of intracellular SV2A protein compared to wild type microglia." (PMID 36406753, 2022).
triple-negative breast carcinoma (1 paper, 2025). An invasive breast carcinoma which is negative for expression of estrogen receptor (ER), progesterone receptor (PR), and human epidermal growth factor receptor 2 (HER2). "In triple-negative breast cancer (TNBC), SV2A has been identified as a biomarker that predicts differential responses to chemotherapy in patient-derived xenografts." (PMID 41424711, 2025).
tuberous sclerosis complex (1 paper, 2017). "In addition, resected tissues from two other causes of ITLE, focal cortical dysplasia (FCD) or tuberous sclerosis complex (TSC), also showed a reduction of SV2A expression." (PMID 28588450, 2017).
neurological disorders (11 papers, 2011 to 2026). "Synaptic vesicle glycoprotein 2 A (SV2A) in human brains is an important biomarker of synaptic loss associated with several neurological disorders." (PMID 40163154, 2025). "PET imaging of synaptic vesicle glycoprotein 2A (SV2A) has proven to be a powerful research tool for neurologic disorders." (PMID 41679926, 2026). "Our research provides evidence that SV2A is an important regulator of AD and lays the foundation for further research on neurological diseases." (PMID 34277597, 2021). "This study provides guidelines and information regarding the influence of the SV2A mechanism on the regulation of AD and possible future research of neurological diseases." (PMID 34277597, 2021). "Several SV2A targeting compounds have been evaluated as PET tracers, including [11C]UCB-J, with the aim to facilitate studies of synaptic density in neurological diseases." (PMID 31784919, 2019).
neurodegenerative disease (10 papers, 2019 to 2025). A disorder of the central nervous system characterized by gradual and progressive loss of neural tissue and neurologic function. "Future research should focus on generating quantitative neuropathological maps of SV2A density in neurodegenerative diseases." (PMID 38699560, 2024). "This manuscript presents a thorough review of synaptic vesicle glycoprotein 2A (SV2A) as a biomarker for synaptic integrity using Positron Emission Tomography (PET) in neurodegenerative diseases." (PMID 38699560, 2024). "Measurement of synaptic density through PET imaging of the synaptic biomarker SV2A opens a new avenue for the investigation of neurodegenerative diseases." (PMID 34025386, 2021). "The review delves into the development of SV2A-specific PET radiotracers, highlighting their advancements and limitations in neurodegenerative diseases." (PMID 38699560, 2024). "Finally, to assess whether SV2A and other synaptic markers are reduced in BDEVs and whether SV2A levels are correlated with other recently proposed CSF panel biomarkers of synaptic dysfunction in neurodegenerative diseases, we performed nonparametric Spearman’s rank correlation analyses." (PMID 40993829, 2025).
tumor (7 papers, 2018 to 2026). "Unexpectedly, the expression of the synaptic protein SV2A in bulk tumour cells showed an even stronger association with response to levetiracetam than SV2A expression in the infiltration zone, suggesting that neuronal structures within the tumour contribute to epileptogenesis." (PMID 30297697, 2018). "The SV2A blockade resulted in a significant reduction of tumor uptake (0.25 ± 0.03 %ID/g, p = 0.025), indicating the desired SV2A imaging specificity." (PMID 34884893, 2021). "According to showed in silico and human data, SV2A stained diffusely and was highly positive in all tumor cells in NEPC lesions." (PMID 33737929, 2021). "To confirm the SV2A-specific uptake of 18F-SynVesT-1 in the NCI-H660 tumor, we performed the blocking study with a co-injection of 19F-SynVesT-1 (0.1 mg, 0.033 μmol)." (PMID 34884893, 2021). "We obtained a similar pattern of SV2A expression by western blot analysis on proteins extracts from tumor cell lines and BMMCs." (PMID 33737929, 2021). "Protein-target validation by immunohistochemistry led us discover by serendipity that SV2A is expressed also by tumor-infiltrating MCs." (PMID 33737929, 2021). "BoNT/A inhibited the proliferation of 4T1 cells, which express the SV2A protein; decreased tumor growth in the preclinical model; and decreased inflammation, associated with fewer blood neutrophils and monocytes, suggesting an immunomodulatory and anti-inflammatory effect." (PMID 42188614, 2026). "At the same time, the brain uptake also showed a drastic decrease (p < 0.01), indicating the successful blockade of SV2A-specific uptake and the SV2A-specific binding of 18F-SynVesT-1 in the NCI-H660 tumor." (PMID 34884893, 2021). "In addition, SV2B expression was substantially higher than that of SV2A and SV2C in TFE3‐RCC tissues, suggesting that padsevonil inhibited tumor progression in TFE3‐RCC primarily by targeting SV2B." (PMID 41199339, 2026). "Importantly, significantly upregulated SV2A protein levels were found in both NEPC cell lines and tumor tissues." (PMID 34884893, 2021). "SV2A was expressed in luminal cells in prostatic intraepithelial neoplasia (PIN) whereas in adenocarcinoma lesions it was negative in almost all tumor cells with few scattered tumor cells showing mild positivity." (PMID 33737929, 2021).
psychiatric disorder (6 papers, 2020 to 2024). A disorder characterized by behavioral and/or psychological abnormalities, often accompanied by physical symptoms. "Studies using these tracers provide evidence that lower brain SV2A levels are associated with a number of neurological and psychiatric disorders relative to healthy controls, and with poorer cognitive function." (PMID 39134769, 2024). "An example is the use of synaptic vesicle glycoprotein (SV2A) as a ligand for Positron Emission Tomography (PET) imaging in a variety of psychiatric disorders." (PMID 38674210, 2024). "So far, most other SV2A PET imaging studies have been cross-sectional case-control studies of neurodegenerative and psychiatric disorders for which causal relationships cannot be determined." (PMID 37814129, 2023). "Currently, [11C]UCB-J and [18F]UCB-H are the two most widely used radiotracers for SV2A PET imaging in patients with neurological or psychiatric disorders, but they both present disadvantages." (PMID 32422902, 2020). "To date, longitudinal studies have shown decreases in SV2A PET measures and worsening of symptoms in neurodegenerative illnesses, supporting a causal role for synaptic changes in these disorders, but there have not been longitudinal studies in psychiatric disorders." (PMID 39134769, 2024).
cancer (4 papers, 2021 to 2026). A tumor composed of atypical neoplastic, often pleomorphic cells that invade other tissues. "SV2A, a protein involved in vesicular release, has emerged as a promising biomarker for various cancers." (PMID 42188614, 2026). "In contrast, SV2A has been reported with high expressions in a broad spectrum of cancer types with NED." (PMID 34884893, 2021). "Among the three synaptic vesicle glycoprotein isoforms (SV2A, SV2B, and SV2C), SV2A is the most dominant one found in cancers." (PMID 34884893, 2021). "Furthermore, the expression of SV2A was also found in correlation with the ability of colorectal cancer stem cells to produce functional neurons, indicative of its role in cancer innervation." (PMID 34884893, 2021). "Taken together, SV2A expression is significantly elevated in NEPC and we reason it may serve as a potential target to develop efficacious theranostics for NEPC and other innervated cancers." (PMID 34884893, 2021).
infection (4 papers, 2010 to 2026). The state of being infected such as from the introduction of a foreign agent such as serum, vaccine, antigenic substance or organism. "First, a primary hippocampal neuronal cell model of SV2A overexpression was constructed by infection with SV2Aoe lentivirus, and the levels of APP metabolites were detected in the cell supernatant." (PMID 41521688, 2026). "In addition, we cultured SV2B and SV2A/B KO spinal cord neurons and observed that while SV2B KO mice were still sensitive to the addition of TeNT, SV2A/B double KO spinal neurons were protected from TeNT; again the neurons were re-sensitized to the toxin after infection with SV2A virus." (PMID 21124874, 2010). "Immunohistochemistry staining further demonstrated that AAV‐miR‐485‐5p infection decreased SV2A expressions without affecting PSD‐95 expressions in DG of DRE rats (14 weeks after SE, 200×)." (PMID 34291586, 2021). "AAV‐miR‐485‐5p infection specifically decreased SV2A expressions without affecting PSD‐95 expressions in DG of DRE rats (14 weeks after SE)." (PMID 34291586, 2021). "We found that miR‐485‐5p overexpression (AAV‐miR‐485‐5p infection) specifically decreased SV2A expression without affecting PSD‐95 expression in DG of DRE rats (14 weeks after SE)." (PMID 34291586, 2021).
adenocarcinoma (2 papers, 2021). A common cancer characterized by the presence of malignant glandular cells. "The bioinformatic analyses revealed an amplified SV2A gene expression in clinical samples of NEPC versus castration-resistant PCa with adenocarcinoma characteristics (CRPC-Adeno)." (PMID 34884893, 2021). "Interestingly, in PIN and adenocarcinoma lesions we found high expression of SV2A by infiltrating stroma cells, particularly MCs and monocytes." (PMID 33737929, 2021).
brain disorder (1 paper, 2017). A disease affecting the brain or part of the brain. "In this review article, we will summarize our present knowledge on SV2A function(s) and its potential role(s) in the pathophysiology of various brain disorders." (PMID 28588450, 2017).
SV2A also shares sentences with these, for which no sentence is quoted: frontotemporal dementia (5 papers); post-traumatic stress disorder (4); Huntington disease (3); ischemic stroke (3); anxiety disorder (2); alcohol use disorder (1); autism (1); cognition (1); cognitive disorder (1); corticobasal degeneration (1); corticobasal syndrome (1); cystitis (1); delirium (1); diseases of the central nervous system (1); Dravet syndrome (1); Focal cortical dysplasia (1); focal epilepsy (1); Focal-onset seizure (1); idiopathic generalized epilepsy (1); migraine (1); Myoclonus (1); neuroendocrine tumours (1); Obesity (1); reflex epilepsy (1); retinal detachment (1); spinal cord injury (1); vascular dementia (1).